RGS2 (regulator of G protein signaling 2)
Description:
Regulates G protein-coupled receptor signaling cascades. Inhibits signal transduction by increasing the GTPase activity of G protein alpha subunits, thereby driving them into their inactive GDP-bound form. It is involved in the negative regulation of the angiotensin-activated signaling pathway. Plays a role in the regulation of blood pressure in response to signaling via G protein-coupled receptors and GNAQ. Plays a role in regulating the constriction and relaxation of vascular smooth muscle (By similarity). Binds EIF2B5 and blocks its activity, thereby inhibiting the translation of mRNA into protein.
Synonyms: G0S8
Tractability: Small molecule: a structure with a bound ligand is known. Antibody: UniProt places it where antibodies can reach, with high confidence; its Gene Ontology location is reachable by antibodies, with high confidence. PROTAC: ubiquitination databases record sites on it.
Safety:
Unwanted effects reported when the protein is acted on. In parentheses: how it was acted on, where the effect was seen, and who reports it.
antipsychotic-induced parkinsonism (source: ClinPGx)
Gene: Protein-coding gene on chromosome 1 (192,809,039 to 192,812,275, forward strand). Ensembl gene ENSG00000116741.
Subcellular location: Cell membrane (Isoform 1); Cytoplasm; Nucleus, nucleolus; Cell membrane (Isoform 2); Cell membrane (Isoform 3); Cell membrane (Isoform 4); Mitochondrion
Subcellular location (Human Protein Atlas): Cytosol
Pathways (Reactome):
Signal Transduction: G alpha (q) signalling events
Gene Ontology:
Molecular function: G-protein alpha-subunit binding; GTPase activator activity; protein binding; calmodulin binding; GTPase activity; adenylate cyclase inhibitor activity; beta-tubulin binding
Biological process: G protein-coupled receptor signaling pathway; negative regulation of cardiac muscle hypertrophy; negative regulation of G protein-coupled receptor signaling pathway; negative regulation of JNK cascade; positive regulation of cardiac muscle contraction; positive regulation of phospholipase C-activating G protein-coupled receptor signaling pathway; regulation of adenylate cyclase-inhibiting adrenergic receptor signaling pathway; regulation of G protein-coupled receptor signaling pathway; relaxation of cardiac muscle; maternal process involved in female pregnancy; negative regulation of cell growth involved in cardiac muscle cell development; negative regulation of glycine import across plasma membrane; negative regulation of translation; positive regulation of neuron projection development; relaxation of vascular associated smooth muscle; response to amphetamine; response to ethanol; spermatogenesis
Cellular component: cytoplasm; cytosol; mitochondrion; nucleus; plasma membrane; cytoplasmic side of plasma membrane; nucleolus
Genetic constraint (gnomAD): Loss-of-function variants: 18 observed, 24.24 expected, observed/expected ratio (o/e) 0.74, 90% interval 0.51 to 1.1. The upper end of that interval is the gene's LOEUF score, 1.1, which puts it in group 4 of 6, group 1 being the genes least tolerant of losing a copy. Missense variants: 237 observed, 247.73 expected, observed/expected ratio (o/e) 0.96, 90% interval 0.86 to 1.07. Synonymous variants: 93 observed, 83.2 expected, observed/expected ratio (o/e) 1.12, 90% interval 0.94 to 1.33.
Homologues: Orthologues: chimpanzee RGS2 (99% identical), macaque RGS2 (99% identical), guinea pig RGS2 (97% identical), rat Rgs2 (97% identical), mouse Rgs2 (96% identical), pig RGS2 (95% identical), dog RGS2 (94% identical), tropical clawed frog rgs2 (68% identical), zebrafish rgs2 (39% identical). Paralogues in human: RGS16 (40% identical), RGS18 (39% identical), RGS3 (39% identical), RGS5 (39% identical), RGS21 (38% identical), RGS8 (38% identical), RGS4 (37% identical), RGS1 (34% identical), RGS13 (32% identical), RGS12 (28% identical), RGS19 (28% identical), RGS20 (27% identical), and 11 more.
Diseases named in the same sentence as RGS2 in open-access papers:
RGS2 is named in the same sentence as 114 diseases in open-access papers, as found by Europe PMC text mining. Sharing a sentence is not in itself a finding about the gene and the disease. The quoted sentences say what the papers report.
Hypertension (26 papers, 2007 to 2025). The presence of chronic increased pressure in the systemic arterial system. "In vivo treatment of RGS2−/− mice with Digoxin stabilized the Regulator of G protein signaling 2 (RGS2), a G(q)-specific GTPase-activating protein, implicated in hypertension and cardiovascular function." (PMID 41154640, 2025). "Pharmacological stabilization of RGS2 would be a feasible therapeutic strategy in pathologies associated with reduced RGS2 protein levels, such as hypertension, heart failure, and asthma." (PMID 40199141, 2025). "Although the frequencies of RGS2 gene variants are often low, the more common c.1114C > G was reported to be associated with hypertension and with lower RGS2 gene expression in some populations." (PMID 39743506, 2025). "Future development of compounds with this mechanism of action would be clinically useful in pathologies associated with low RGS2 protein levels, including hypertension, heart failure, and asthma." (PMID 40199141, 2025). "The second candidate gene study also identified another SNP rs4606 from the RGS2 gene associated with PE and later-life hypertension." (PMID 38455895, 2023). "The second study investigated a single genetic variant (rs4606) in the Regulator of G Protein Signaling 2 (RGS2) gene to check its association with later-life hypertension 15-years following PE." (PMID 38455895, 2023). "Several RGS2 mutations, causing reduced expression due to an increased rate of proteasomal degradation, have also been associated with hypertension in humans." (PMID 35327608, 2022). "Several in vivo studies have demonstrated the association of RGS2 inhibition with atrial tachycardia, hypertension, and cardiac hypertrophy." (PMID 35745791, 2022). "Genetic studies have identified Rgs2 single nucleotide polymorphisms (SNPs) in hypertension cohorts from several regions around the world." (PMID 29654907, 2018). "The RGS2 protein acts as an inhibitor of physiological vasoconstrictive pathways, and a low RGS2 level is associated with hypertension and obesity, two conditions that predispose to preeclampsia." (PMID 27558088, 2016). "The 3′ UTR C1114G polymorphism of RGS2 (rs4606) is associated with low RGS2 levels and has been connected to hypertension and obesity." (PMID 27558088, 2016). "Wild-type RGS2 has a very short protein half-life and human SNPs associated with hypertension (e.g. Q2L in a Japanese population) are characterized by low protein levels in vitro." (PMID 25970626, 2015). "Using kidney cross-transplantation, Gurley and colleagues previously showed that RGS2 deficiency in the kidney is sufficient to cause hypertension." (PMID 26193676, 2015). "Pharmacological targeting of this mechanism provides a novel therapeutic approach to hypertension, anxiety, and other diseases associated with RGS2 dysregulation." (PMID 25970626, 2015). "Over the past decade it has become clear that low RGS2 protein levels are associated with diseases as diverse as hypertension, heart failure, prostate cancer, and anxiety." (PMID 25970626, 2015). "Rgs2-null mice are hypertensive and polymorphisms in RGS2 have been implicated in human hypertension." (PMID 21179467, 2010). "LOF variants of RGS2 may contribute to hypertension due to their role in regulating AT1R activity and signaling, including in Bartter’s/Gitelman’s syndrome." (PMID 39743506, 2025). "Loss of RGS9 results in a visual disorder in which patients cannot adapt to changes in light, while loss of RGS2 amplifies signaling by angiotensin AT1 receptor that may contribute to hypertension and cardiac remodeling (also regulated by RGS14)." (PMID 39743506, 2025). "Rgs2 deficiency also mediates hypertension by increasing vascular tone, which is proved by the enhanced shrinkage of mesenteric obstacles and renal interlobar arteries, and by the elevated hypertension responses to ANG as well." (PMID 37649067, 2023).
Hypertension (continued). "Moreover, mutations in RGS2 gene are associated with human hypertension and reduced RGS2 expression has been demonstrated in hypertensive populations." (PMID 34493304, 2021). "Our results suggest that RGS2 might be involved in the pathogenesis of preeclampsia particularly in overweight women and contribute to their increased risk for hypertension and other types of cardiovascular disease later in life." (PMID 27558088, 2016). "Certain Rgs2 gene mutations have been linked to human hypertension." (PMID 26193676, 2015). "Renal RGS2 deficiency is sufficient to cause hypertension in mice; however, the pathological mechanisms are unknown." (PMID 26193676, 2015). "RGS2 deficiency in mice leads to hypertension and cardiac hypertrophy." (PMID 23285140, 2012). "Both heterozygous and homozygous RGS2-null mice exhibited a similar level of marked hypertension, suggesting that a naturally occurring mutation that affects the level of RGS2 protein may have a significant impact on blood pressure regulation." (PMID 20981351, 2010). "Thus, this polymorphism in the RGS2 gene may be a common predisposing factor for the development of hypertension in pregnancy (preeclampsia) and hypertension outside of pregnancy." (PMID 24593135, 2014). "RGS2 is also shown to have a role in vascular function, with a reduced expression of RGS2 in the vasculature contributing to hypertension." (PMID 38974519, 2024). "Further evidence has shown that women carrying this RGS2 SNP and suffering PE have the increased probability of developing hypertension after delivery." (PMID 37649067, 2023). "For example, RGS2 deficiency increases angiotensin II (AngII) type 1 (AT1) receptor signaling, leading to hypertension, and RGS2 and RGS14 regulate cardiac remodeling." (PMID 36671648, 2023). "A meta-analysis has shown that RGS2 1891-1892del TC polymorphism and CYP4A11 T8590C polymorphism were associated with hypertension risk." (PMID 31906879, 2020). "Conversely, hypertension in RGS2-/- mice was abolished following receipt of kidneys from wild type donors." (PMID 26193676, 2015). "It inhibits signaling through a number of GPCRs mediating vasoconstriction, such as Angiotensin II and Endothelin-1 receptors and consequently RGS2-/- mice exhibit hypertension and prolonged responses to vasoconstrictor agents." (PMID 25970626, 2015). "RGS2 deficiency in mice is known to augment GPCR-induced vasoconstriction and impair endothelium-dependent vasodilation, which are hallmarks of essential hypertension." (PMID 26193676, 2015). "RGS2 takes part in the regulation of normal vascular tone and blood pressure, as observed in knockout mice; reduction or abnormal function of RGS2 contributes to hypertension." (PMID 25031678, 2014). "The regulator of G protein signaling 2 (RGS2) is a negative G protein regulator, which selectively regulates G⍺q signaling, a potential cause of hypertension." (PMID 38974519, 2024). "There is strong evidence linking Rgs2 and hypertension in humans." (PMID 29654907, 2018). "Thus, increased sodium retention due to increased tubular sodium reabsorptive capacity mediated by ENaC likely contributes to hypertension in RGS2-/-mice." (PMID 26193676, 2015). "The absence of RGS2 in the kidney plays a causal role in the development of hypertension in RGS2-/- mice." (PMID 26193676, 2015). "In agreement with this hypothesis, Gurley and colleagues previously showed that hypertension in RGS2 mice could be enhanced by high salt diet." (PMID 26193676, 2015). "Prior evidence and findings presented herein are consistent with the hypothesis that primary renal microvascular defects play a causal role in the development of hypertension in the absence of RGS2." (PMID 26193676, 2015). "However, because RBF and GFR were attenuated in RGS2-/- mice, these changes in renal autoregulation may be maladaptive and further exacerbate or help perpetuate hypertension." (PMID 26193676, 2015).
Hypertension (continued). "Based on the majority of our previous study population, the population-based HUNT2 study, we wanted to explore whether rs4606 in RGS2 is associated with development of hypertension after pregnancy, which to our knowledge has not been investigated previously." (PMID 24593135, 2014). "However, changes in common to caveolin-1 expression and G protein signalling, through attenuation of Rgs2 and Rgs5, may contribute to hypertension through augmentation of vasoconstrictor pathways and provide potential targets for common drug development." (PMID 17986358, 2007). "Interestingly, Rgs2 was also decreased in aortic smooth muscle during L-NAME-induced hypertension." (PMID 17986358, 2007). "The data suggests a mild-to-moderate change in kidney function with AV-RGS2 transfection, which was expected as the upregulation of RGS2 impacted overall sympathetic activity and, thus, kidney function in ANG II-induced hypertension." (PMID 38974519, 2024). "Our results describe a novel role of RGS2 in the PVN for regulating blood pressure, sympathetic activation, and kidney function in hypertension." (PMID 38974519, 2024). "Another example is the CUL4B•DDB1•FBXO44-dependent ubiquitination of RGS2 (regulator of G protein signaling 2), a protein that regulates vasoconstriction and the lack of which leads to hypertension in mice." (PMID 35327608, 2022). "With little to no studies being done on the RGS2 protein on G-protein signaling on the central mechanisms of blood pressure control, we view it as important to examine how these interactions affect sympathetic reflex and the progression of hypertension." (PMID 38974519, 2024). "The aim of our study was to characterize the association of clinical and genetic risk factors such as: ACE genotype (rs17997552, rs1800764, rs4459609) and RGS2 (rs2746071) with the development of hypertension (HT) and non-dipping phenomenon in patients with type 1 diabetes mellitus (T1DM)." (PMID 24562335, 2014).
breast carcinoma (20 papers, 2012 to 2024). "Known as an inhibitor of G-protein signaling, the dysregulation of RGS2 has been implicated in tumor initiation and progression in breast cancer, acute myeloid leukemia, and prostate cancer." (PMID 36276067, 2022). "On the contrary, RGS2 repression seems to be linked to reduced OS in breast cancer, bladder cancer, and stage II/III colorectal cancer." (PMID 36230542, 2022). "Studies have shown that the aberrant expression of RGS2 is associated with the tumorigenesis of breast cancer, prostate cancer, ovarian cancer, lymphoma and acute myeloid leukemia." (PMID 29108247, 2017). "The association between HITT/RGS2 and PD-L1 in breast cancer tissues." (PMID 37014700, 2023). "Besides, the expression of RGS2 might be related to the survival of breast cancer patients, and the low expression of RGS2 might cause a lower survival rate and poor prognosis." (PMID 33500709, 2021). "RGS2 has been reported to be related to several cancers, such as breast cancer, prostate cancer, ovarian cancer, and acute myeloid leukemia." (PMID 39594230, 2024). "RGS2 was also found to be decreased in breast cancer tissues, and its downregulation was more evident in the advanced breast cancers." (PMID 37014700, 2023). "The clinical correlation between HITT/PD-L1 and RGS2/PD-L1 expression was also detected in breast cancer tissues." (PMID 37014700, 2023). "RGS2 overexpression has been shown to inhibit proliferation in MCF7 breast cancer cells and HEK293T cells." (PMID 35386334, 2022). "The molecular analysis of the isolated epithelial cells showed RGS2 overexpression in breast cancer cells and the modulation of the signal transduced by the oxytocin receptor for the protein." (PMID 35453754, 2022). "To further explore the roles of RGS2 in breast cancer tissue, we collected 30 breast cancer samples paired with adjacent tissues from patients to examine IHC assays of RGS2." (PMID 33500709, 2021). "The IHC results showed that the protein expression of RGS2 was downregulated in human breast cancer samples compared with that in adjacent tissues." (PMID 33500709, 2021). "The expression of RGS2 in breast cancer is lower than that in normal tissues, and overexpression of RGS2 inhibits MCF-7 cell proliferation." (PMID 33712565, 2021). "The overexpression of RGS2 in breast cancer cells reduces the protein level of testicular specific Y-like protein 5 (TSPYL5) to disturb calcium pumps, thereby inhibiting cellular proliferation." (PMID 33500709, 2021). "Next, increased expression of Dact1 is known to inhibit proliferation of breast cancer cells through inhibition of Wnt/β-catenin signaling, while increased expression of Rgs2 is known to suppress growth of MCF7 and HEK293T breast carcinoma cells." (PMID 26517510, 2015). "Through bioinformatics analysis, we found that the expression of RGS2 might be related to the pathological stage of breast cancer in the breast cancer cohort of the TCGA database." (PMID 33500709, 2021). "Thus, RGS2 was upregulated in MCF7 breast cancer cells, inhibiting cell proliferation." (PMID 37999477, 2023). "Additionally, we reported that an epigenetic small-molecule inhibitor of HDACs, PCI-24781, could target RGS2 to reduce cell proliferation, metastasis, and differentiation, resulting in cell death during breast cancer progression." (PMID 34993131, 2021). "In summary, these results suggest that RGS2 could be a candidate tumor suppressor in breast cancer." (PMID 33500709, 2021). "Therefore, we assumed that the upregulation of RGS2 in breast cancer cells might be induced by the activation of histone acetylation after treatment with an HDAC inhibitor." (PMID 33500709, 2021). "Furthermore, a negative association between HITT/RGS2 and PD-L1 expression was detected in vivo in human breast cancers, suggesting that HITT may inhibit PD-L1 expression in vivo." (PMID 37014700, 2023).
breast carcinoma (continued). "RGS2, RGS4 and RGS6 repress cell growth, whose expression is decreased in breast cancer cells, compared to the normal cells." (PMID 37118788, 2023). "Similar to CHN2 and RGS2, we predict that a significant number of genes upregulated in ERBB2 overexpressing luminal breast cancers are indeed PR-driven." (PMID 22697792, 2012). "For example, some RGS proteins including RGS4, RGS16, RGS2, RGS6 and RGS17 negatively regulate the progression of breast cancer, whereas RGS20 protein exerts the positive effects on potentiating the carcinogenesis of breast cancer." (PMID 37118788, 2023). "In contrast, induction of RGS2-HA expression resulted in no suppression of cell growth in the breast cancer cell line MCF-7, which is not dependent on mutations in Gαq as the oncogenic driver." (PMID 35452684, 2022). "In addition, RGS2 depletion reversed anti-tumor effect and inhibition of calcium influx induced by PCI-24781 treatment in breast cancer cells." (PMID 33500709, 2021). "Further analyses showed that PCI-24781 inhibited Gαq-PLCβ3-mediated calcium signaling by activating the expression of regulator of G-protein signaling 2 (RGS2) to reduce cell proliferation, metastasis, and differentiation, resulting in cell death in breast cancer." (PMID 33500709, 2021). "Furthermore, lower expression levels of RGS2 in breast cancer samples compared with adjacent tissues were confirmed by four published datasets, TCGA BRAC, GSE36295, GS42568, and GSE54002, suggesting that RGS2 might be a candidate tumor suppressor in breast cancer." (PMID 33500709, 2021).